ATRX (ATRX chromatin remodeler)
Diseases named in the same sentence as ATRX in open-access papers (continued):
Sharing a sentence is not in itself a finding about the gene and the disease.
glioma (continued). "Moreover, ATRX is a target gene responsible for the oncogenic role of miR-1269a in glioma." (PMID 33194637, 2020). "The loss of ATRX promotes tumor growth and damages non-homologous end-linked DNA repair of gliomas." (PMID 33194637, 2020). "Finally, we found that ATRX overexpression could reverse the suppressive effects of miR-1269a overexpression on the proliferation and invasion of glioma cells." (PMID 33194637, 2020). "Moreover, two of the broad CNAs arising with ATRX deficiency in NHAs, involving 12p gain and 14q loss, recapitulated events commonly seen in the IDHmut-noncodel glioma subtype and associated with relatively unfavorable prognosis when present." (PMID 30808951, 2019). "Mutations of ATRX and of TERT are not sufficient as possible indications for ALT- and TEL-TMM because loss of ATRX coexist with TEL-TMM in some cell lines and melanomas, which can show ATRX and TERT mutations in parallel, while they are mutually exclusive in in glioma." (PMID 31750255, 2019). "The first group had the longest median overall survival (96 months) in comparison with patients with IDH1 mutations and ATRX loss (51 months), while the shortest median overall survival was in glioma patients who did not harbor any of those signatures (13 months)." (PMID 27834917, 2016). "ATRX expression is significantly upregulated in several cancer types, including ACC, GBM, lower-grade gliomas (LGG), and pancreatic adenocarcinoma (PAAD), compared to their normal counterparts." (PMID 40282990, 2025). "The ATRX, OLIG2, MGMT, and IDH2 networks highlight key molecular interactions that contribute to glioma development, progression, and therapeutic resistance." (PMID 40282990, 2025). "Moreover, previous studies have shown that the loss of ATRX increases sensitivity to DNA-damaging agents, suggesting that ATRX mutations may represent a crucial point of therapeutic intervention for high-grade NF1 gliomas and LGm6 sporadic gliomas." (PMID 40277798, 2025). "Although DKI can predict glioma grades (HGG or LGG) stably, the utility of DKI for predicting glioma genotypes, like IDH, ATRX, MGMT genetic statuses, remains controversial." (PMID 40352771, 2025). "Radiomic features were also used to determine the genetic profiles of ATRX, IDH1/2, MGMT and 1p19q in gliomas." (PMID 38486342, 2024).
glioma (continued). "Interestingly, activating H3.3 mutations triggered ALT in pediatric high-grade glioma regardless of ATRX mutation status, indicating that similarly, H3.3 upregulation may have functional implications in ALT neuroblastomas." (PMID 39635126, 2024). "Material and Method: We identified 84 patients with grade II-IV glioma with IDH, ATRX, 1p / 19q and TERT status." (PMID 34558656, 2022). "Moreover, the EGFR and MUC16 mutations were also significantly enriched in cases within high‐risk group, while mutations in CIC, NOTCH1, ATRX, and CDH12 occurred more frequently in the low‐risk group, these characteristics are consistent with the update WHO CNS5 classification of glioma." (PMID 35985661, 2022). "Mutant IDH1 promotes glioma growth in cells with PDGFA amplification and/or inactivation of CDKN2A, ATRX and PTEN." (PMID 35382567, 2022). "This explains the differences in CTCF motif frequency observed between ATRX-KO and ATRX-wildtype, as well as between IDH-A and IDH-O, IDH-mutant glioma specimens." (PMID 34763709, 2021). "We conclude that ATRX KO leads to a significant, global decrease in CTCF binding in IDH-mutant glioma." (PMID 34763709, 2021). "This is consistent with the fact that all our IDH-A specimens (and over 86% of the IDH-A patient population) are ATRX mutant while the IDH-O samples (and most IDH-O gliomas) have ATRX intact." (PMID 34763709, 2021). "Our results showed that constructed multiparametric model from MRI radiomics features can identify IDH1, ATRX, MGMT, and EGFR in preoperative MRI scans of patients with glioma." (PMID 34056604, 2021). "We found an overexpression of DLGAP5, NEK2, and PBK, while the expression of SF1, PTEN, ATRX, and DAXX was downregulated in tumor tissues as compared to normal tissues of the patients with glioma." (PMID 35095717, 2021). "This is consistent with our human glioma scATAC-seq data, in which CTCF recognition motifs are the most over-represented in ATRX-wildtype specimens." (PMID 34763709, 2021). "Subsequently, the radiomics signatures were utilized to predict the genetic profile of ATRX, IDH1/2, MGMT and 1p19q co-deletion, as well as differentiating low-grade glioma from high-grade glioma." (PMID 34944806, 2021).
glioma (continued). "We now expand on that finding to show that monocytic-lineage cells derived from the peripheral blood more heavily infiltrate IDH-A and ATRX-KO/IDH1R132H gliomas, compared to IDH-O and ATRX-wildtype/IDH1R132H glioma, respectively." (PMID 34763709, 2021). "DNA methylation assigned NF1-glioma to LGm6, a poorly defined IDH wild-type subgroup enriched with ATRX mutations, which may represent a point of therapeutic intervention, as previous studies have shown that loss of ATRX increases sensitivity to DNA-damaging agents." (PMID 31906320, 2020). "Moreover, it was reported that ATRX complex may contribute to temozolomide resistance in glioma." (PMID 33194637, 2020). "Studies predicting glioma genes based on radiomics mainly focused on the IDH, 1p/19q, MGMT, ATRX, and EGFR genes, which all agreed that radiomics was an excellent noninvasive method for predicting the genetic status of glioma." (PMID 32509858, 2020). "To characterize the role of G4-mediated genomic instability in glioma biology, we inactivated ATRX in isogenic normal human astrocyte (NHA) and glioma stem cell (GSC) models." (PMID 30808951, 2019). "Candidate genes should include oncogenic drivers ATRX and/or PDGFRA as they are present at significant frequency in lower grade gliomas." (PMID 29953513, 2018). "Herein, we have generated functional ATRX knockouts in four telomerase-positive, ALT-negative human glioma cell lines: MOG-G-UVW, SF188, U-251 and UW479." (PMID 30226859, 2018). "However, understanding the pathogenesis of gliomas lacking ATRX is more crucial before specific treatment regimens can be developed; there still exists a large knowledge gap in how these subset of gliomas behave differently from the others and what underlies their tumor progression." (PMID 29034211, 2017). "The tumor (negative for IDH1 (R132H) staining, lacking 1p/19q codeletion, with preserved ATRX) exhibited moderate atypia and focal microvascular proliferation, suggestive of a high-grade glioma." (PMID 41596318, 2026). "However, the correlation between genetic alterations in gliomas and PET tracer accumulation has only been investigated using certain genes, including IDH, ATRX, and TERT." (PMID 40786409, 2025). "Finally, we selected the following seven indicators as the mIHC panel: IDHR132H, ATRX, EGFR, CDKN2A, HIP1R, GFAP (glial fibrillary acidic protein, marker of glioma cells), and DAPI (4ʹ,6‐diamidino‐2‐phenylindole, marker cell nucleus)." (PMID 40264576, 2025).
glioma (continued). "Understanding the relationship between ATRX status and ABCG2 expression could provide insights into the prognosis of glioma patients and inform treatment strategies." (PMID 38542090, 2024). "ATRX: From the studies examined above, we find that the overexpression of ATRX in glioma cells does not significantly affect patient prognosis or overall survival." (PMID 38674026, 2024). "NEC gliomas are IDH1 non-mutant gliomas that express ATRX, lack necrosis or microvascular proliferation, and do not have chromosome 7 gain, chromosome 10 loss, EGFR amplification, or TERT promoter mutation." (PMID 39135755, 2024). "In high-grade gliomas ALT frequently occurs in H3.3G34R-mutant tumors independent of ATRX alterations, indicating a functional link between impaired H3.3 function and ALT." (PMID 39635126, 2024). "We found that ATRX-d (monoallelic: PR-AUC-E = 0.21, AUROC = 0.71; biallelic: PR-AUC-E = 0.23, AUROC = 0.76) and IDH1-d (monoallelic: PR-AUC-E = 0.24, AUROC = 0.82) in CNS cancers were both predicted by a decreased number of SBS signature 8 mutations." (PMID 36883553, 2023). "In our longitudinal analysis of three paired initial and recurrent or metastatic high-grade gliomas, the key genetic drivers (e.g., NF1, CDKN2A, ATRX) were shared truncal events while only chromosomal copy number aberrations were private to initial or recurrent/metastatic tumors." (PMID 35945463, 2022). "A diagnosis of an H3G34-mutant glioma or HGAP would not be made on the basis of ATRX IHC even in cases where those diagnoses are suspected, and sequencing or methylation profiling would be necessary, respectively." (PMID 36397144, 2022). "In pediatric high‐grade glioma, the G34R mutation in H3.3 triggers ALT, irrespective of the ATRX status." (PMID 35920001, 2022). "They performed immunofluorescence assay using glioma cell model and discovered that FADD overexpression increased temozolomide (TMZ)-induced DNA damage in glioma cells, whereas FADD knockdown decreased TMZ-induced DNA damage in ATRX knockout glioma cells." (PMID 36348274, 2022). "The ratio was higher than gliomas in non-midline structures, corresponding to the fact that H3K27M mutated gliomas seem to predominantly result from lengthening of telomeres through ATRX mutation." (PMID 35756637, 2022). "Ibrutinib and niclosamide have shown positive results in the treatment of glioma cells, regardless of the ATRX status." (PMID 35406561, 2022). "There are studies suggesting ATRX mutations are associated with better prognosis in IDH-mutant, low-grade glioma patients without 1p/19q co-deletion." (PMID 35991838, 2022).
glioma (continued). "Next, other common glioma biomarkers, such as MGMT status, 1q/19q codeletion and ATRX loss, were not included in the analysis of the signature." (PMID 33828990, 2021). "Moreover, we observed that DDX60 was significantly overexpressed in glioma with IDH wild-type, ATRX wild-type, MGMT unmethylated as well as TERT promoter mutated." (PMID 34178649, 2021). "Moreover, additional genetic events, such as ATRX, TERT, and BRAF, which also frequently occur in IDH-mutant glioma, should be considered in future investigations." (PMID 34440884, 2021). "Likewise, 96% (43/45) of oligodendrogliomas and 37% (11/30) of astrocytomas had retained ATRX staining, with a statistically significant differential expression between the two IDH Mut glioma lineages (P ≤ 0.05)." (PMID 34020723, 2021). "This approach would reserve 1p/19q codeletion testing only to IDH-mutant gliomas with retention of both ATRX and H3K27me3 or non-conclusive ATRX immunostainings." (PMID 34165590, 2021). "ATRX loss alone, however, is insufficient to induce ALT since knockdown of ATRX in two TEL+ human glioma cell lines, 8-MG-BA and Hs-683, did not increase the formation of C-circles or APBs." (PMID 34069193, 2021). "Finally, increased expression of TRIM22 correlated with other features of more aggressive gliomas, including wild-type IDH1 (P < 0.001) and wild-type ATRX (P = 0.0054)." (PMID 32814880, 2021). "ATRX loss was a favorable prognostic factor only in WHO II astrocytoma patients, but in all the glioma patients, it has no statistically significant (Median OS was 28 to 25, p=0.457)." (PMID 32047544, 2020). "The presence or absence of inactivating ATRX and DAXX mutations present a strong correlation with ALT in many tumor types including gliomas." (PMID 29616301, 2018). "All of the glioma lines assessed retain expression of both ATRX and DAXX, as assessed by immunoblotting and immunohistochemistry, while U2-OS, a well-characterized ALT-positive osteosarcoma cell line harboring an ATRX deletion, lacks ATRX expression." (PMID 30226859, 2018). "The resulting three categories were as follows: I-A (IDH1/ATRX mutation), I-CF (IDH1/CIC/FUBP1 mutation), and I-X gliomas (not I-A or I-CF)." (PMID 29026176, 2017). "Moreover, the expression of some key factors in gliomas were detected by QPCR, such as IDH1, TERT, EGFR, PTEN, ATRX." (PMID 28199986, 2017). "A fraction of gliomas (e.g., IDH-mutated tumors with or without both ATRX mutation and 1p/19 co-deletion) cannot be classified according to the proposed algorithm." (PMID 24559763, 2014).